SCARF2 (scavenger receptor class F member 2)
Description:
Probable adhesion protein, which mediates homophilic and heterophilic interactions. In contrast to SCARF1, it poorly mediates the binding and degradation of acetylated low density lipoprotein (Ac-LDL) (By similarity).
Synonyms: SREC-II; SREC2; HUMZD58C02; NSR1; SRECRP-1; VDEGS
Tractability: Antibody: UniProt predicts a signal peptide or a membrane-spanning region. PROTAC: ubiquitination databases record sites on it.
Gene: Protein-coding gene on chromosome 22 (20,424,584 to 20,437,944, reverse strand). Ensembl gene ENSG00000244486.
Subcellular location: Membrane
Subcellular location (Human Protein Atlas): Nucleoplasm; Cytosol; Nuclear bodies
Gene Ontology:
Molecular function: protein binding; scavenger receptor activity
Biological process: heterophilic cell-cell adhesion; vesicle-mediated transport
Cellular component: focal adhesion; membrane
Genetic constraint (gnomAD): Loss-of-function variants: 41 observed, 53.65 expected, observed/expected ratio (o/e) 0.76, 90% interval 0.59 to 0.99. The synonymous counts are far from expectation, so gnomAD's model fits this gene poorly and the ratio says little. Missense variants: 1,139 observed, 1,015.3 expected, observed/expected ratio (o/e) 1.12, 90% interval 1.07 to 1.18. Synonymous variants: 603 observed, 455.33 expected, observed/expected ratio (o/e) 1.32, 90% interval 1.24 to 1.42.
Homologues: Orthologues: chimpanzee SCARF2 (99% identical), macaque SCARF2 (98% identical), dog SCARF2 (92% identical), pig SCARF2 (91% identical), guinea pig SCARF2 (90% identical), rat Scarf2 (85% identical), mouse Scarf2 (84% identical), tropical clawed frog scarf2 (56% identical), zebrafish SCARF2 (45% identical). Paralogues in human: SCARF1 (36% identical), CRB2 (20% identical), CRB3 (3% identical).
Diseases named in the same sentence as SCARF2 in open-access papers:
SCARF2 is named in the same sentence as 32 diseases in open-access papers, as found by Europe PMC text mining. Sharing a sentence is not in itself a finding about the gene and the disease. The quoted sentences say what the papers report.
van den Ende-Gupta syndrome (3 papers, 2016 to 2023). Van den Ende-Gupta syndrome is a very rare syndrome characterized by blepharophimosis, arachnodactyly, joint contractures, and characteristic dysmorphic features. "We identified a 2-bp deletion in SCARF2 in dogs with severe mandibular prognathia and other skeletal abnormalities and established a canine model for van den Ende-Gupta syndrome (VDEGS)." (PMID 27187611, 2016). "SCARF2 defects have been reported in the rare human bone disease van den Ende-Gupta syndrome." (PMID 27187611, 2016).
breast carcinoma (2 papers, 2024 to 2025). "Through differential expression analysis and mutual information, we identified seven genes (NOL4, STAR, C8G, NEIL1, SLC46A3, FRMD6, and SCARF2) that are potential biomarkers in breast cancer." (PMID 39199284, 2024). "We identified seven potential genes within breast cancer: NOL4, STAR, C8G, NEIL1, SLC46A3, FRMD6, and SCARF2." (PMID 39199284, 2024).
chronic obstructive pulmonary disease (2 papers, 2024 to 2025). A chronic and progressive lung disorder characterized by the loss of elasticity of the bronchial tree and the air sacs, destruction of the air sacs wall, thickening of the bronchial wall, and mucous accumulation in the bronchial tree. "Scavenger receptor class F member 2 (SCARF2; > −2.4-fold), whose decline in plasma has been associated with chronic obstructive pulmonary disease, was also downregulated." (PMID 41205594, 2025).
glioblastoma (2 papers, 2024). The most malignant astrocytic tumor (WHO grade IV). "Increased SCARF2 expression has been detected in glioblastoma, an age‐associated neurologic disorder, compared to regular brain tissue." (PMID 38263575, 2024). "Kim and coworkers conducted a study that delves into the expression patterns of SCARF2, particularly in glioblastoma (GBM), revealing heightened expression levels compared to normal brain tissue." (PMID 38558360, 2024).
glioma (2 papers, 2016 to 2024). A benign or malignant brain and spinal cord tumor that arises from glial cells (astrocytes, oligodendrocytes, ependymal cells). "This may suggest that hsa-miR-139-3p is a repressor of glioma malignant progression and its up-regulated target gene SCARF2 may be a risk gene for glioma." (PMID 27013589, 2016). "Especially, in the miRNA down-regulated overlap group, hsa-miR-139-3p target SCARF2 pair is included and hsa-miR-139-3p is consistently down-regulated in the glioma grades III and IV." (PMID 27013589, 2016). "Utilizing The Cancer Genome Atlas database, comprehensive analysis underscores the widespread expression of SCARF2 in GBM, with elevated SCARF2 levels correlating with an unfavourable prognosis amongst glioma patients." (PMID 38558360, 2024).
prostate carcinoma (2 papers, 2011 to 2022). A carcinoma that arises from epithelial cells of the prostate gland. "A few of these (regions associated with ADAMTS1, SCARF2, and DSCR9) were tested further, and in combination, showed ~100% sensitivity and ~85% specificity for prostate cancer compared to matched adjacent benign tissues." (PMID 21669002, 2011).
atherosclerosis (1 paper, 2015). A disease characterized by the build-up of fatty material and calcium deposition in the arterial wall resulting in partial or complete occlusion of the arterial lumen. "Other up-regulated genes that are also targets of miR-193 included mediators of obesity, related inflammatory cytokine and leptin signaling (JAK2) as well as atherosclerosis (SCARF2/SREC-I)." (PMID 26258540, 2015).
Caffey disease (1 paper, 2016). Caffey disease is an osteosclerotic dysplasia characterized by acute inflammation with massive subperiosteal new bone formation usually involving the diaphyses of the long bones, as well as the ribs, mandible, scapulae, and clavicles. "We identified a novel candidate gene, SLC37A2, for the corresponding human disease, infantile cortical hyperostosis, also known as Caffey disease, and implicated SCARF2 and FAM20C variants in the canine forms of van den Ende-Gupta and Raine syndromes, respectively." (PMID 27187611, 2016).
DiGeorge syndrome (1 paper, 2018). "Simultaneous analysis of the NGS H‐TAD gene panel and SNP array revealed that the heterozygous deletion of SCARF2 was part of a 22q11.2 deletion (i.e., DiGeorge syndrome) (3.2Mb; hg19; chr22:20779645_20792061)." (PMID 29907982, 2018).
hepatocellular carcinoma (1 paper, 2018). A malignant tumor that arises from hepatocytes. "Thus, it is clear that the genes argsyn, ScarF2, LGR5, and rasgbd are probably associated with liver pathological process, including glycolipid metabolism disorder, hepatocellular carcinoma, and autophagy." (PMID 29670865, 2018).
Krebs 2 carcinoma (1 paper, 2022). "The obtained data confirmed the strong overexpression of Mreg, Prg4, Col3a1, Selp, Marco, and Fgfr1 genes in Krebs-2 carcinoma, as well as Cdh11, Col4a5, Vcam1, Megf6, Scarf2, Scart1, and Cd14 genes in HH47." (PMID 36555446, 2022).
liver cancer (1 paper, 2025). An epithelial or non-epithelial malignant neoplasm that arises from the liver. "Intriguingly, the top-ranked protein SCARF2 is a predictive biomarker of liver cancer." (PMID 40287427, 2025).
migraine (1 paper, 2022). "Finally, SCARF2 which is involved in the degradation of acetylated low-density lipoprotein (LDL) might be linked to a higher level of LDL and its related metabolites in migraine patients." (PMID 35546551, 2022). "Among the identified 36 blood proteins with pleiotropic effects on migraine at SNPs within LD-independent loci, five proteins have two or more pleiotropic SNPs with migraine, including four SNPs for ERBB3, three SNPs for F2R, and two SNPs for B3GNT2, VEGFA and SCARF2." (PMID 35546551, 2022).
mood disorder (1 paper, 2021). A cognitive disorder a disturbance in which the person's mood is hypothesized to be the main underlying feature. "Of these, the association between SCARF2 and mood disorders reached phenome-wide significance in the PheWAS." (PMID 34715901, 2021). "Integrating genetic information with the diagnosis of mood disorders in the clinical data allowed us to find a new candidate, SCARF2, at 22q11.2 that we were unable or underpowered to detect in the ascertained bipolar data alone." (PMID 34715901, 2021). "In the phenome-wide association study, we found seventeen significant gene-trait pairs, including psychosis (NPIPB11, SLX1B) and mood disorders (SCARF2), and overall enrichment of mental traits." (PMID 34715901, 2021).
Raine syndromes (1 paper, 2016). "Mutations in SCARF2 and FAM20C have been associated with the human van den Ende-Gupta and Raine syndromes that include numerous features similar to the affected dogs." (PMID 27187611, 2016). "Mutations in the SCARF2 and FAM20C genes have been associated with the human van den Ende-Gupta and Raine syndromes." (PMID 27187611, 2016).
schizophrenia (1 paper, 2021). A major psychotic disorder characterized by abnormalities in the perception or expression of reality. "SCARF2 has recently been proposed as a driver of schizophrenia within a fine-mapping study within CNV carriers." (PMID 34715901, 2021).
α-synucleinopathies (1 paper, 2024). "Hub genes of the α-synucleinopathy-associated modules included RBP4, C1orf70 (TMEM240), and SCARF2, which have been previously implicated in PD." (PMID 38995454, 2024).
cancer (3 papers, 2021 to 2024). A tumor composed of atypical neoplastic, often pleomorphic cells that invade other tissues. "This research contributes valuable insights into the potential utility of SCARF2 in the realm of cancer diagnosis and treatment." (PMID 38558360, 2024). "SCARF2 (Scavenger Receptor Class F Member 2) is involved in endocytosis, lipid metabolism, and cell adhesion and is up-regulated in various cancers, promoting tumor progression." (PMID 39199284, 2024).
Mendelian diseases (1 paper, 2018). "The six genes (SCARF2, RD3, COL9A3, FAM161A, RASGRP1 and DLX6) in common between novel contigs, human Mendelian diseases, and hereditary diseases in dogs are significant in known disease phenotypes in humans and animal models." (PMID 30022108, 2018).
SCARF2 also shares sentences with these, for which no sentence is quoted: tumor (2 papers); demyelination (1); disorders of iris (1); gastric cancer (1); neurologic disorder (1); neuropathies (1); Obesity (1); psychosis (1); renal failure (1); rheumatic disease (1); Sjögren’s syndrome (1); spinocerebellar ataxia (1); systemic sclerosis (1).